SLC22A25 (solute carrier family 22 member 25)
Synonyms: UST6; HIMTP; MGC120420
Tractability: Small molecule: it belongs to a druggable protein family. Antibody: UniProt predicts a signal peptide or a membrane-spanning region.
Gene: Protein-coding gene on chromosome 11 (63,158,437 to 63,243,599, reverse strand). Ensembl gene ENSG00000196600.
Subcellular location: Membrane
Gene Ontology:
Molecular function: transmembrane transporter activity
Biological process: transmembrane transport
Cellular component: membrane
Genetic constraint (gnomAD): Loss-of-function variants: 39 observed, 43.42 expected, observed/expected ratio (o/e) 0.9, 90% interval 0.69 to 1.17. The upper end of that interval is the gene's LOEUF score, 1.17, which puts it in group 5 of 6, group 1 being the genes least tolerant of losing a copy. Missense variants: 694 observed, 613.44 expected, observed/expected ratio (o/e) 1.13, 90% interval 1.06 to 1.21. Synonymous variants: 250 observed, 219.67 expected, observed/expected ratio (o/e) 1.14, 90% interval 1.03 to 1.26.
Homologues: Orthologues: chimpanzee SLC22A25 (97% identical), zebrafish oatx (37% identical), zebrafish si:dkey-166k12.1 (28% identical), zebrafish slc22a4 (28% identical), zebrafish slc22a21 (27% identical), zebrafish slc22a5 (26% identical), Drosophila melanogaster Orct (26% identical), Drosophila melanogaster Orct2 (25% identical), Caenorhabditis elegans oct-1 (25% identical), zebrafish si:dkey-119m7.4 (24% identical), Drosophila melanogaster CG6356 (24% identical), Drosophila melanogaster CG42269 (23% identical), and 42 more. Paralogues in human: SLC22A9 (72% identical), SLC22A10 (59% identical), SLC22A24 (58% identical), SLC22A12 (45% identical), SLC22A11 (45% identical), SLC22A6 (36% identical), SLC22A8 (36% identical), SLC22A7 (31% identical), SLC22A13 (29% identical), SLC22A5 (27% identical), SLC22A4 (25% identical), SLC22A3 (24% identical), and 10 more.
Diseases named in the same sentence as SLC22A25 in open-access papers:
SLC22A25 is named in the same sentence as 2 diseases in open-access papers, as found by Europe PMC text mining. Sharing a sentence is not in itself a finding about the gene and the disease. The quoted sentences say what the papers report.
multiple sclerosis (1 paper, 2018). A progressive autoimmune disorder affecting the central nervous system resulting in demyelination. "rs4957048 is associated with multiple sclerosis/ulcerative colitis, and it was associated with an editing site located downstream of SLC22A25." (PMID 29527417, 2018).
SLC22A25 also shares sentences with these, for which no sentence is quoted: ulcerative colitis (1 paper).